CHPF (chondroitin polymerizing factor)
Description:
Non-catalytic component of CHSY1-CHPF2 and CHSY3-CHPF2 chondroitin sulfate synthase complexes. CHPF associates with catalytically active chondroitin synthases (CHSY1/3) within heterodimeric complexes. Plays an essential role for the formation of a stable and functional chondroitin sulfate polymerase complexes. [Isoform 2]: May facilitate PRKN transport into the mitochondria. In collaboration with PRKN, may enhance cell viability and protect cells from oxidative stress.
Synonyms: CSS2; CHSY2; CHPF1
Tractability: Antibody: UniProt predicts a signal peptide or a membrane-spanning region. PROTAC: ubiquitination databases record sites on it; its protein half-life has been measured.
Gene: Protein-coding gene on chromosome 2 (219,538,949 to 219,543,818, reverse strand). Ensembl gene ENSG00000123989.
Subcellular location: Golgi apparatus, Golgi stack membrane (Isoform 1); Cytoplasm, cytosol; Cytoplasm, cytosol (Isoform 3); Mitochondrion; Mitochondrion matrix (Isoform 2)
Subcellular location (Human Protein Atlas): Cytosol; Centrosome; Vesicles
Pathways (Reactome):
Metabolism: CS-GAG biosynthesis
Gene Ontology:
Molecular function: acetylgalactosaminyltransferase activity; glucuronosyl-N-acetylgalactosaminyl-proteoglycan 4-beta-N-acetylgalactosaminyltransferase activity; N-acetylgalactosaminyl-proteoglycan 3-beta-glucuronosyltransferase activity; protein-macromolecule adaptor activity; glycosyltransferase activity
Biological process: chondroitin sulfate proteoglycan biosynthetic process
Cellular component: cytosol; mitochondrial matrix; mitochondrion; Golgi membrane; Golgi apparatus; Golgi cisterna membrane
Genetic constraint (gnomAD): Loss-of-function variants: 34 observed, 47.47 expected, observed/expected ratio (o/e) 0.72, 90% interval 0.54 to 0.95. The upper end of that interval is the gene's LOEUF score, 0.95, which puts it in group 4 of 6, group 1 being the genes least tolerant of losing a copy. Missense variants: 961 observed, 1,024.9 expected, observed/expected ratio (o/e) 0.94, 90% interval 0.89 to 0.99. Synonymous variants: 489 observed, 463.5 expected, observed/expected ratio (o/e) 1.05, 90% interval 0.98 to 1.14.
Homologues: Orthologues: chimpanzee CHPF (99% identical), macaque CHPF (99% identical), pig CHPF (97% identical), dog CHPF (95% identical), mouse Chpf (94% identical), rat Chpf (93% identical), rabbit CHPF (86% identical), guinea pig CHPF (82% identical), tropical clawed frog chpf (60% identical), zebrafish chpfb (54% identical), zebrafish chpfa (53% identical), Drosophila melanogaster Chpf (29% identical), and 1 more. Paralogues in human: CHPF2 (57% identical), CHSY3 (21% identical), CHSY1 (21% identical), B4GALNT4 (15% identical), B4GALNT3 (13% identical), CSGALNACT2 (13% identical), CSGALNACT1 (12% identical).
Diseases named in the same sentence as CHPF in open-access papers:
CHPF is named in the same sentence as 23 diseases in open-access papers, as found by Europe PMC text mining. Sharing a sentence is not in itself a finding about the gene and the disease. The quoted sentences say what the papers report.
glioma (7 papers, 2020 to 2025). A benign or malignant brain and spinal cord tumor that arises from glial cells (astrocytes, oligodendrocytes, ependymal cells). "In summary, the results of our study showed that CHPF was overexpressed in glioma and was positively associated with the malignant clinical pathological characteristics of patients with glioma." (PMID 37851364, 2023). "Chondroitin polymerizing factor (CHPF; > −2.7-fold), a type II transmembrane protein, is involved in tissue remodeling and extracellular matrix synthesis, and its downregulation is associated with reduced glioma proliferation and migration." (PMID 41205594, 2025). "Furthermore, CHPF expression was positively correlated with malignant clinical pathological characteristics and was associated with a worse survival rate in patients with glioma." (PMID 37851364, 2023). "In this study, we showed that HNF4A was enriched in the promoter region of CHPF and stimulated the expression of CHPF in glioma." (PMID 37851364, 2023). "In our study, inhibition of glioma by downregulation of CHPF was reversed by overexpression of MAD1L1, which showed that CHPF promoted glioma malignance through regulation of MAD1L1 expression." (PMID 37851364, 2023). "Total protein from 15 glioma samples and 15 normal brain tissue samples was extracted to characterize the role of CHPF in glioma." (PMID 37851364, 2023). "In contrast, the expression levels of P21 and P27, which are cell cycle inhibitors, were increased in response to CHPF knock-down in glioma cells." (PMID 37851364, 2023). "To further characterize the biological functions of CHPF in the development and tumorigenesis of gliomas, we analyzed proteins in the U251 cell line that potentially interacted with CHPF using IP and LC-MS/MS assays." (PMID 37851364, 2023). "Silencing CHPF expression inhibited proliferation, colony formation, migration, and cell cycle of glioma cells." (PMID 37851364, 2023). "In this study, we found that CHPF expression was significantly upregulated in GBM and was positively associated with malignant clinical pathological characteristics of patients with glioma." (PMID 37851364, 2023). "Western blot analysis showed that CHPF protein expression was significantly higher in glioma samples than that in normal brain tissue." (PMID 37851364, 2023). "Immunohistochemistry analysis also indicated that CHPF protein was expressed at higher levels in glioma samples." (PMID 37851364, 2023). "The results showed that CHPF was expressed at significantly higher levels in GBM than in low grade glioma (LGG)." (PMID 37851364, 2023). "The results showed that CHPF was directly interacted with MAD1L1 to promote glioma progression by regulating cell cycle." (PMID 37851364, 2023). "In this study, we found that CHPF was up-regulated in glioma tissues and was positively correlated with malignant clinical pathological characteristics of patients with glioma." (PMID 37851364, 2023). "In this study, we explored the molecular functions of CHPF and its associations with Mitotic arrest deficient 1-like 1 (MAD1L1) in glioma." (PMID 37851364, 2023). "Our previous study showed that silencing CHPF expression inhibited glioma cell proliferation in vitro, but the molecular mechanisms by which CHPF contributes to development of glioma have not been characterized." (PMID 37851364, 2023). "Our previous study showed that knock-down of CHPF inhibited glioma cell proliferation in vitro, but the potential molecular mechanisms of CHPF in development of glioma had not been previously characterized." (PMID 37851364, 2023). "Currently, CHPF has been reported to be upregulated in lung adenocarcinoma, non‐small‐cell lung cancer, gliomas and malignant melanoma, etc., suggesting that it plays an important role in tumor progression." (PMID 33301643, 2021). "There results showed that CHPF played an important role in promoting glioma tumorigenesis in vivo." (PMID 37851364, 2023).
glioma (continued). "Furthermore, CHPF promoted glioma tumorigenesis through direct interaction with MAD1L1 and regulation of MAD1L1 expression." (PMID 37851364, 2023). "We also measured the expression of CHPF in five glioma cell lines and SVG cells." (PMID 37851364, 2023). "Furthermore, inhibition of glioma proliferation through silencing of CHPF was confirmed in an intracranial tumor mouse model." (PMID 37851364, 2023). "More importantly, CHPF is abnormally upregulated in several types of cancer and has been proven to be a potential tumor promoter in colorectal cancer, head and neck squamous cell carcinoma, and glioma." (PMID 34564711, 2021). "Furthermore, overexpression of CHPF in glioma was confirmed using the IHC and western blot assays." (PMID 37851364, 2023). "In addition, Chromatin Immunoprecipitation (ChIP)-PCR analysis showed that HNF4A bound to the CHPF promoter region, which indicated that the transcription factor hepatocyte nuclear factor 4A (HNF4A) could regulate the expression of CHPF in glioma cells." (PMID 37851364, 2023). "Moreover, silencing CHPF suppressed glioma malignance in vivo." (PMID 37851364, 2023). "Moreover, it has been reported that CHPF could promote glioma cell growth and restrain apoptosis." (PMID 33301643, 2021).
lung adenocarcinoma (7 papers, 2020 to 2024). A carcinoma that arises from the lung and is characterized by the presence of malignant glandular epithelial cells. "unveiled the inhibitory effect of CHPF knockdown on the advancement of lung adenocarcinoma, both in experimental models and in clinical specimens." (PMID 38775031, 2024). "CHPF is highly expressed in lung adenocarcinoma and can promote tumor cell growth, invasion and metastasis, and inhibit tumor cell apoptosis." (PMID 36277284, 2022). "Consistently, previous studies reported that downregulation of CHPF could significantly suppress lung adenocarcinoma cell proliferation, apoptosis and the cell cycle." (PMID 33301643, 2021).
breast carcinoma (6 papers, 2013 to 2024). "We then assessed the association between CHPF-associated proteoglycans (PGs) and signaling pathways in breast cancer datasets." (PMID 38770553, 2024). "Here, we found that chondroitin polymerizing factor is upregulated in breast carcinoma and associated with worse prognosis according to bioinformatic analysis." (PMID 33301643, 2021). "In the current study, CHPF transcript expression was negatively correlated with DNA methylation in breast cancer, and CHPF transcript expression was associated with poorer prognosis while methylation of the CHPF DNA cg03176520 locus was associated with better survival." (PMID 35372047, 2022). "Previous studies identified chondroitin polymerizing factor (CHPF; also known as chondroitin sulfate synthase 2) is the critical enzyme regulating CS accumulation in breast cancer tissue." (PMID 38770553, 2024). "Results indicated that the expression of CHPF and SDC1 was tightly associated within primary breast cancer tissue, and high expression of both genes exacerbated patient prognosis." (PMID 38770553, 2024). "Transforming growth factor beta (TGF-β) signaling was implicated in the regulation of CHPF and SDC1 in breast cancer cells." (PMID 38770553, 2024). "We observed that CHPF was significantly upregulated in breast cancer tissues and correlated with poor prognosis." (PMID 35372047, 2022). "CHPF promotes proliferation, migration, invasion of the breast cancer cell lines MCF-7 and SUM1315, and is significantly enriched in pathways associated with the ECM-receptor interaction and PI3K-AKT pathway." (PMID 35372047, 2022). "At present, only a few publications focus on the role of CHPF in non-small cell adenocarcinoma, hepatocellular carcinoma, and breast cancer." (PMID 35372047, 2022). "More specifically, the role of CHPF in breast cancer is to promote proliferation, invasion and migration." (PMID 36277284, 2022). "In this paper, we investigated the role of CHPF in breast cancer prognosis prediction and proposed a combined bioinformatics and basic experimental approach." (PMID 35372047, 2022). "CHPF was extensively abundant in breast cancer cell lines MCF-7 as well as SUM1315, and so these two cell lines were selected for follow-up studies." (PMID 35372047, 2022). "Upregulation of CHPF in breast cancer promotes malignant behavior of cancer cells and is associated with poorer survival in breast cancer, possibly through ECM-receptor interactions and the PI3K-AKT pathway." (PMID 35372047, 2022). "Here, we analyzed the expression of the CHPF gene in 14 pairs of tumors and normal tissues and found that the CHPF gene was significantly increased in breast cancer tissues." (PMID 35372047, 2022). "Although other PGs may also be involved in CHPF-regulated breast cancer malignancy, this study provides the first evidence that a CS synthase participates in the regulation of macropinocytosis in cancer cells by supporting SDC1 expression on cancer cells." (PMID 38770553, 2024). "Our research also proved a significant increase in CHPF expression in breast cancer tissues." (PMID 35372047, 2022). "Our study provides new research direction for the role of CHPF in breast cancer." (PMID 35372047, 2022). "However, the role of CHPF in breast carcinoma (BRCA) and its underlying mechanism are still not fully elucidated." (PMID 33301643, 2021). "We developed a novel GRG signature of six GRGs, including CACNA1H, CHPF, IRS2, NT5E, SDC1 and ATP6AP1, to predict survival and guide individual therapy in breast cancer." (PMID 36277284, 2022). "We found that the protein levels of CACNA1H, CHPF, SDC1 and ATP6AP1 were higher in breast cancer tissues compared with normal tissues, while the expression levels of IRS2 and NT5E were comparatively lower in breast cancer tissues, and the expression of them is consistent with mRNA level." (PMID 36277284, 2022).
colorectal cancer (5 papers, 2020 to 2024). A primary or metastatic malignant neoplasm that affects the colon or rectum. "In this investigation, we have identified CHPF as a promoter of colorectal cancer (CRC) progression, thus suggesting its potential as a therapeutic target for CRC treatment." (PMID 38775031, 2024). "Nevertheless, the role of CHPF in colorectal cancer (CRC) remains undisclosed and unexplored." (PMID 38775031, 2024). "However, the precise functional implications of CHPF in colorectal cancer (CRC) development have yet to be elucidated, as there is currently limited knowledge in this area." (PMID 38775031, 2024). "In addition, CHPF has been observed to be abnormally expressed in colorectal cancer and head and neck squamous cell cancer." (PMID 34564711, 2021). "Studies have shown that CHPF expression is upregulated in colorectal cancer, laryngeal cancer, and brain glioma and that the overexpression of CHPF may be closely related to tumor occurrence and development." (PMID 32348423, 2020). "Our results are in accordance with the results of previous studies reporting that CHPF was upregulated in NSCLC, glioblastoma, colorectal cancer and laryngeal cancer." (PMID 33301643, 2021).
gastric cancer (5 papers, 2021 to 2025). A primary or metastatic malignant neoplasm involving the stomach. "Analysis of the association between CHPF expression and the characteristics of gastric cancer patients was conducted to confirm the significance of the CHPF levels." (PMID 34564711, 2021). "Moreover, the underlying mechanism of the CHPF-induced regulation of gastric cancer was explored through RNA sequencing followed by bioinformatics analysis." (PMID 34564711, 2021). "This study is the first comprehensive investigation of the upregulated expression of CHPF in gastric cancer tissues in comparison with normal tissues." (PMID 34564711, 2021). "CHPF expression in gastric cancer tissues was detected by immunohistochemistry and correlated with gastric cancer patient prognosis." (PMID 34564711, 2021). "In summary, the upregulated expression of CHPF in gastric cancer tissues and the positive correlation between high expression of CHPF and poor prognosis were revealed in this study." (PMID 34564711, 2021). "Simultaneously, the promotive effects of CHPF overexpression on the development and progression of gastric cancer were also proven." (PMID 34564711, 2021). "It should be noted that knockdown of CHPF in gastric cancer cells inhibited cell proliferation and colony formation, promoted apoptosis through the regulation of apoptosis-related biomarkers, and suppressed the migration ability of the cells." (PMID 34564711, 2021). "Through high-throughput sequencing of SGC-7901 cells with or without CHPF knockdown, the present study identified E2F1 as a potential downstream effector of CHPF and revealed the possible mechanism by which CHPF regulates gastric cancer." (PMID 34564711, 2021). "All these results suggest that E2F1 and CHPF share a similar role in gastric cancer, with E2F1 acting as a downstream target." (PMID 34564711, 2021). "Taken together, these results revealed the potential role of CHPF as a prognostic indicator and tumor promoter in the development of gastric cancer." (PMID 34564711, 2021). "This study showed, for the first time, that CHPF is a potential prognostic indicator and tumor promoter in gastric cancer whose function is likely carried out through the regulation of E2F1." (PMID 34564711, 2021). "The results demonstrated that CHPF was upregulated in gastric cancer tissues compared with normal tissues, and a high CHPF expression level was correlated with Tumor cell infiltration, advanced tumor stage, and poor prognosis." (PMID 34564711, 2021). "CHPF expression in clinical specimens was detected by immunohistochemical analysis to explore the role of CHPF in gastric cancer." (PMID 34564711, 2021). "Overall, these results indicate that knockdown of CHPF may alleviate the development of gastric cancer by inhibiting cell proliferation, suppressing migration, and inducing apoptosis." (PMID 34564711, 2021). "Moreover, the highly abundant expression and upregulation of CHPF in gastric cancer cell lines compared with the human gastric epithelial cell line GES1 was also detected by qPCR." (PMID 34564711, 2021). "Furthermore, CHPF knockdown significantly inhibited the migration ability of gastric cancer cells (> 20% inhibition in AGS and >50% inhibition in SGC-7901 cells, P < 0.01)." (PMID 34564711, 2021). "CHPF may promote gastric cancer development by regulating cell proliferation, colony formation, cell apoptosis and cell migration, while knockdown induced the opposite effects." (PMID 34564711, 2021). "In gastric cancer tissues, CHPF was found to be significantly upregulated, and its expression correlated with tumor infiltration and advanced tumor stage and shorter patient survival in gastric cancer." (PMID 34564711, 2021).